KRT23 (keratin 23)
Synonyms: K23; DKFZP434G032; HAIK1; CK23; MGC26158
Tractability: No criterion of Open Targets' tractability assessment is met for any kind of drug.
Gene: Protein-coding gene on chromosome 17 (40,922,700 to 40,937,646, reverse strand). Ensembl gene ENSG00000108244.
Subcellular location (Human Protein Atlas): Intermediate filaments; Cytosol
Pathways (Reactome):
Developmental Biology: Developmental Lineage of Pancreatic Ductal Cells; Formation of the cornified envelope; Keratinization
Gene Ontology:
Molecular function: protein binding; structural constituent of skin epidermis; structural molecule activity
Biological process: epithelial cell differentiation; intermediate filament organization; morphogenesis of an epithelium
Cellular component: cytoskeleton; cytosol; keratin filament
Genetic constraint (gnomAD): Loss-of-function variants: 31 observed, 42.1 expected, observed/expected ratio (o/e) 0.74, 90% interval 0.55 to 0.99. The upper end of that interval is the gene's LOEUF score, 0.99, which puts it in group 4 of 6, group 1 being the genes least tolerant of losing a copy. Missense variants: 430 observed, 470.53 expected, observed/expected ratio (o/e) 0.91, 90% interval 0.84 to 0.99. Synonymous variants: 168 observed, 182.23 expected, observed/expected ratio (o/e) 0.92, 90% interval 0.81 to 1.05.
Homologues: Orthologues: chimpanzee KRT23 (97% identical), macaque KRT23 (95% identical), pig KRT23 (81% identical), rabbit KRT23 (81% identical), dog KRT23 (80% identical), rat Krt23 (80% identical), mouse Krt23 (79% identical), guinea pig KRT23 (77% identical), tropical clawed frog krt23 (44% identical). Paralogues in human: KRT15 (43% identical), KRT16 (43% identical), KRT14 (42% identical), KRT12 (41% identical), KRT17 (41% identical), KRT10 (41% identical), KRT13 (41% identical), KRT27 (40% identical), KRT24 (40% identical), KRT9 (39% identical), KRT19 (39% identical), KRT36 (39% identical), and 56 more.
Diseases named in the same sentence as KRT23 in open-access papers:
KRT23 is named in the same sentence as 43 diseases in open-access papers, as found by Europe PMC text mining. Sharing a sentence is not in itself a finding about the gene and the disease. The quoted sentences say what the papers report.
colon cancer (11 papers, 2011 to 2024). "Promoter binding analysis revealed that Smad4 was associated with KRT23 expression in migratory colon cancer cells, and KRT23 exhibited Smad4-dependent upregulation, thus influencing cell signal transduction and eventually promoting colon cancer cell migration." (PMID 33204716, 2020). "In addition, KRT23 has been reported to be associated with several cancers, such as colon cancer, pancreatic cancer and hepatocellular carcinoma." (PMID 26672748, 2015). "Downregulation of the keratin 23 (Krt23) gene has been shown to reduce proliferation in colon cancer cells, although its function has not been explored in pituitary cells." (PMID 34223822, 2021). "Zhang found that overexpression of KRT23 increased the activity of telomerase reverse transcriptase, which then promoted colon cancer cell migration." (PMID 33204716, 2020). "KRT23 (keratin 23), which was recently identified as a putative immunologic target for colon cancer prevention, was also significantly up-regulated in the tumors." (PMID 26517809, 2015). "SW948 and LS1034 colon cancer cells, either with an empty vector or with a stable KRT23 knockdown, were irradiated with 0 GY or 5 GY of γ-rays." (PMID 24039993, 2013). "In conclusion, here we show evidence that KRT23 expression is epigenetically regulated in colon mucosa and that KRT23 is upregulated in colon cancer due to demethylation of the KRT23 promoter." (PMID 24039993, 2013). "In an initial approach, lentiviral mediated knockdown of KRT23 was applied to the human colon cancer cell line SW480." (PMID 24039993, 2013). "Knockdown of KRT23 rendered colon cancer cells more sensitive to irradiation and reduced proliferation of the KRT23 depleted cells compared to irradiated control cells." (PMID 24039993, 2013). "Construct sh-1506 was further used to study the effect of KRT23 knockdown in three different colon cancer cell lines." (PMID 24039993, 2013). "In addition, in colon cancer cells the upregulation of KRT23 affects the expression of crucial mediators that were involved in apoptosis and the cell cycle." (PMID 39771533, 2024). "KRT23 knockdown decreases proliferation and affects the DNA damage response of colon cancer cells." (PMID 35646092, 2022). "Furthermore, researchers have identified that KRT23 is localized in the Golgi apparatus in the cytoplasm, highly expressed in colon cancer, and that overexpression of KRT23 promoted colon cancer cell proliferation and migration." (PMID 33204716, 2020). "In conclusion knockdown of KRT23 in colon cancer cells strongly decreased the expression of several molecules necessary for the establishment of DNA repair complexes, which may result in a less efficient DNA repair upon irradiation damages." (PMID 24039993, 2013). "As early stage adenocarcinomas already express moderate to high levels of KRT23 in vivo, we wanted to know whether depletion of KRT23 may affect the molecular and cellular functions of colon cancer cells." (PMID 24039993, 2013). "In conclusion, KRT23 depleted colon cancer cells may be restricted in their assembly of functional G1/S complexes." (PMID 24039993, 2013). "Colon cancer cells depleted from KRT23 compared to control cells." (PMID 24039993, 2013). "Neither the KRT23 transcript nor the K23 protein has been shown to be a prognostic marker in colon cancer; however, we observed a tendency that patients with stage II colon adenocarcinomas with high KRT23 transcript levels seemed to have a lower recurrence rate." (PMID 24039993, 2013). "In vitro analyses confirmed that KRT23 depletion significantly decreased the cellular proliferation of colon cancer cell lines, and markedly decreased the expression of genes involved in DNA damage response, mainly molecules of the double strand break repair homologous recombination pathway." (PMID 24039993, 2013).
colon cancer (continued). "In microsatellite stable colon cancer, KRT23 expression is highly increased, and this may have a protective function counteracting the proliferation and survival of cells." (PMID 23071592, 2012). "VAV3, ACSL6, GNG4, and KRT23 were significantly enriched in gene set defined as “downregulated genes discriminating between MSI and MSS colon cancers”." (PMID 31008109, 2019). "Decreased expression upon KRT23 knockdown was confirmed at the protein level for key molecules MRE11A, E2F1, RAD51 and BRCA1 and knockdown of KRT23 rendered colon cancer cells more sensitive to irradiation." (PMID 24039993, 2013).
colorectal cancer (7 papers, 2017 to 2024). A primary or metastatic malignant neoplasm that affects the colon or rectum. "KRT23 has been implicated as an oncogene in liver cancer and colorectal cancer." (PMID 33579221, 2021). "The aim of this study is to characterize a novel mechanism based on miR-195-5p/KRT23 in colorectal cancer." (PMID 39771533, 2024). "In this work, we aimed to evaluate the involvement of KRT23 in colorectal cancer, focusing on its molecular regulation." (PMID 39771533, 2024). "Previous studies have presented evidence of aberrant expression of KRT23 in various tumor tissues, including pancreatic cancer, colorectal carcinoma, and hepatocellular carcinoma." (PMID 33204716, 2020). "KRT23 was reported to be involved in cell migration and cell invasion in colorectal cancer." (PMID 33204716, 2020). "Like FOXQ1, KRT23 has been connected with cancer progression in colorectal cancer." (PMID 31404997, 2019). "LINC01315 was also found to be correlated with DPEP1, KRT23, ASCL2, AXIN2, and DUSP4 in colorectal cancer." (PMID 35470736, 2022).
hepatocellular carcinoma (6 papers, 2015 to 2025). A malignant tumor that arises from hepatocytes. "KRT23 is a member of the keratin family and an acidic keratin expressed in various cancer types, including pancreatic, colorectal, and hepatocellular carcinomas." (PMID 40260298, 2025). "Next, we investigated the modulation of KRT23 protein levels in human hepatoma cells upon HCV challenge." (PMID 31216713, 2019). "By analyzing the KRT23 protein levels in hepatoma cells, we detected the disappearance of the designated 33-kDa KRT23 isoform, but increased signal intensities of the 48 kDa KRT23 isoform in the HCV challenged cells compared with the mock challenged cells." (PMID 31216713, 2019). "However, subsequent analysis of PHHs and hepatoma cells supported the hypothesis that KRT23 is upregulated in an HCV-dependent manner on a single cell level." (PMID 31216713, 2019). "Keratin 23 (KRT23) is an acidic type I keratin that was first identified in pancreatic cancer and subsequently was detected as a tumor-specific antigen in hepatocellular carcinoma (HCC) patients." (PMID 39771533, 2024). "Taken together, the obtained data indicated that KRT23 was directly induced by HCV challenge in PHHs and hepatoma cells." (PMID 31216713, 2019). "To investigate the role of endogenous KRT23 in hepatoma cells, we generated two independent CRISPR/Cas9-mediated knockout (KO) cell lines of KRT23 with guide RNAs targeting the positive strand of exon 2 (KO #1) and the negative strand of exon 6 (KO #2)." (PMID 31216713, 2019). "Therefore, we aimed to analyze the KRT23 regulation upon HCV challenge in more detail and setup experiments with both primary cells and hepatoma cell-lines." (PMID 31216713, 2019). "In this study, we investigated KRT23 mRNA levels in datasets from liver biopsies of chronic hepatitis C (CHC) patients and in primary human hepatocytes experimentally infected with HCV, in addition to hepatoma cells." (PMID 31216713, 2019).
gastric cancer (4 papers, 2022 to 2024). A primary or metastatic malignant neoplasm involving the stomach. "In gastric cancer, KRT23 knockout inhibited the proliferation and arrested cell cycle progression through a reduced phosphorylation of ERK1/2 and p38." (PMID 39771533, 2024). "Research have revealed that KRT23 is a subtype-specific prognostic factor for gastric cancer." (PMID 35646092, 2022).
liver cancer (4 papers, 2020 to 2023). An epithelial or non-epithelial malignant neoplasm that arises from the liver. "The effect of PPARα activation is the opposite in the liver cancer, PPARα activation enhanced the expression of MYC, which in turn enhanced the expression of the Krt23, a downstream target gene of the PPARα, thereby promoted the proliferation of the liver cancer cells." (PMID 33132907, 2020). "KRT23 is PPARA dependent and also highly expressed in human liver cancer." (PMID 36796223, 2023). "For example, Keratin 23 was considered a PPAR‐α dependent, MYC‐amplified oncogene that might remove rate‐limiting constraints on hepatocyte proliferation and lead to liver cancer." (PMID 33931972, 2021).
ovarian carcinoma (4 papers, 2020 to 2023). A malignant neoplasm originating from the surface ovarian epithelium. "Studies have reported that KRT23 overexpression promotes the migration of ovarian cancer cells via epithelial–mesenchymal transition." (PMID 35814465, 2022). "However, the role of KRT23 in ovarian cancer (OC) remains unclear." (PMID 33204716, 2020). "Furthermore, the Amniota-specific KRT8, KRT19, KRT23 and KRT80 were shown to be up-regulated in ovarian cancer." (PMID 36949761, 2023).
liver disease (3 papers, 2012 to 2019). "Recently, the dramatic changes in KRT23 expression levels in the context of liver disease were reported." (PMID 31216713, 2019). "For example, keratin 23 (KRT23) was reported as a stress-inducible protein, whose expression levels correlate with the severity of liver disease." (PMID 31216713, 2019). "The results confirmed a dramatic upregulation of KRT23 in patients with AH (n = 51) compared with normal livers (n = 7) and other liver diseases including compensated cirrhosis (n = 10), hepatitis C (n = 10, HCV) and NASH (n = 14), (P < 0.001)." (PMID 27752144, 2016). "We then assessed serum KRT23 concentration and plasma free and microparticle-bound proteins by ELISA as a potential biomarker of liver disease." (PMID 27752144, 2016). "Additionally, KRT23, strongly upregulated in several human cancers, was suggested to be a ductular reaction marker, since its levels correlate with liver disease severity." (PMID 31216713, 2019). "Finally, we analyzed if KRT23 gene expression correlated with the degree of portal hypertension, a major pathophysiological event in these patients." (PMID 27752144, 2016). "We observed a higher degree of portal hypertension in patients with higher levels of hepatic KRT23 expression compared to those with lower levels of hepatic KRT23 expression (hepatic venous pressure gradient 14 ± 6 mmHg vs. 21 ± 5 mmHg, respectively; P < 0.001)." (PMID 27752144, 2016). "Nevertheless, the functional role of KRT23 in liver or liver diseases needs to be resolved." (PMID 23071592, 2012). "Thus, the idea to use KRT23 as a serum marker to monitor hepatic disease progression may be extended by the usage of KRT23 to monitor liver regeneration." (PMID 31216713, 2019). "Taking the findings of Guldiken and colleagues that KRT23 is a stress-induced marker into account, the decline of KRT23 levels highlights the regenerative potential of the liver and the potential of DAA to revert the progression of liver diseases." (PMID 31216713, 2019). "KRT23 has not yet been described to be expressed in liver or liver disease." (PMID 23071592, 2012).
alcoholic hepatitis (2 papers, 2023 to 2025). Acute hepatitis resulting from ingestion of alcohol. "The most strongly upregulated gene in this cluster is Krt23, which has been described to be the gene that has the clearest upregulation in livers from alcoholic hepatitis patients compared to NASH patients." (PMID 37415213, 2023). "Gene expression profiles show that KRT23 is moderately highly expressed in steatohepatitis, suggesting that KRT23 may be a potential biomarker for alcoholic hepatitis and a marker for predicting HCC progression." (PMID 40649881, 2025).
colorectal tumor (2 papers, 2017 to 2022). "The effect of KRT23 on tumor proliferation was further examined in nude mice with human colorectal tumor xenografts." (PMID 28749462, 2017). "Interestingly, KRT23 could promote the proliferation of colorectal tumor cells by increasing telomerase reverse transcriptase expression." (PMID 35814465, 2022).
staphylococcus aureus infection (2 papers, 2020 to 2024). An infectious process in which the bacteria Staphylococcus aureus is present. "Notably, Staphylococcus aureus infection was identified as one of the key pathways in which Cluster35 participated, due to its influence on several Keratin-related genes, such as KRT13, KRT23, and KRT27." (PMID 38448858, 2024).
adenoma (1 paper, 2013). A neoplasm arising from the epithelium. "The methylation status of the KRT23 promoter was assessed in 40 colon tissue samples (six normal mucosa, six adenoma, five MSI and 23 MSS adenocarcinoma tissues) using Illumina Bead arrays interrogating CG-sites at position cg06378617 and cg22392708 located in the KRT23 promoter." (PMID 24039993, 2013). "In this study we provide evidence that the KRT23 promoter is methylated in normal mucosa with no or very low expression of KRT23, while most adenomas and adenocarcinomas with high KRT23 expression were found to be hypomethylated." (PMID 24039993, 2013).
bladder cancer (1 paper, 2021). "Previous studies have reported abnormal expression of KRT23 in numerous tumor tissues, including bladder cancer." (PMID 34885040, 2021). "In summary, using a series of bioinformatics and retrospective analyses, the present study identified a subset of seven genes (CDC20, CDKN2A, CTSV, FOXM1, KRT23, MAGEA6, and S100A9), which were significantly associated with progression and prognosis of bladder cancer." (PMID 34885040, 2021). "The PPI network analysis of three databases identified the following subsets of DEGs, including CDC20, CDKN2A, CTSV, FOXM1, KRT23, MAGEA6, and S100A9, which were significantly upregulated in bladder cancer." (PMID 34885040, 2021). "The expression profile of CDC20, CDKN2A, CTSV, FOXM1, KRT23, MAGEA6, and S100A9 were significantly higher in bladder cancer specimens compared with normal bladder tissue in patients." (PMID 34885040, 2021). "A total of seven genes, including CDKN2A, CDC20, CTSV, FOXM1, MAGEA6, KRT23, and S100A9 were confirmed with strong prognostic values in bladder cancer and validated by qRT-PCR conducted in various human bladder cancer cells representing stage-specific disease progression." (PMID 34885040, 2021).
breast carcinoma (1 paper, 2019). "In summary, we retrospectively identified five bone metastases‐related genes (KRT23, REEP1, SPIB, ALDH3B2, and GLDC) and constructed a gene expression signature‐based nomogram (GESBN) model for breast cancer patients by bioinformatics analysis." (PMID 30575323, 2019).
cholestasis (1 paper, 2016). Impairment of the bile flow caused by obstruction within the liver, or outside the liver in the bile duct system. "To explore the expression of KRT23 in the ductular reaction we used a well-characterized experimental model which causes advanced fibrosis, cholestasis and progenitor cell expansion (i.e. DDC diet)." (PMID 27752144, 2016). "Overall, these results indicate that KRT23 is expressed in the ductular reaction and LPCs in livers with cholestasis and progenitor cell expansion." (PMID 27752144, 2016).
Cirrhosis (1 paper, 2016). A chronic disorder of the liver in which liver tissue becomes scarred and is partially replaced by regenerative nodules and fibrotic tissue resulting in loss of liver function. "Thus, KRT23 may be expressed in cases of steatohepatitis with cirrhosis." (PMID 27752144, 2016). "KRT23 expression was also upregulated, but to a lesser extent, in patients with HCV (P < 0.005) and compensated cirrhosis (P < 0.001) compared to the control liver samples." (PMID 27752144, 2016).
colon adenocarcinoma (1 paper, 2013). "In a previous study we showed that phosphokeratin KRT23 was strongly upregulated in colon adenocarcinomas compared to normal colon mucosa." (PMID 24039993, 2013). "In previous studies, we identified the KRT23 transcript and K23 protein to be strongly upregulated in colon adenocarcinomas compared to normal mucosa." (PMID 24039993, 2013). "Keratin 23 (KRT23) is strongly expressed in colon adenocarcinomas but absent in normal colon mucosa." (PMID 24039993, 2013).
endometriosis (1 paper, 2025). The growth of functional endometrial tissue in anatomic sites outside the uterine body. "We observed that, in all five algorithms, the expression levels of CDH1 and KRT23 were inversely related to the risk of developing endometriosis." (PMID 40140093, 2025).
fibrosis (1 paper, 2016). the formation of excess fibrous connective tissue in an organ or tissue in a reparative or reactive process. "Then, we explored if LPS further increases the expression of Krt23 in livers with advanced fibrosis." (PMID 27752144, 2016).
inflammatory bowel disease (1 paper, 2018). A spectrum of small and large bowel inflammatory diseases of unknown etiology. "Along with those already mentioned, other top up-regulated DEGs such as Uck2, Krt23, Pcsk9, and S100a11 have also been associated with cancer or inflammatory bowel disease (IBD), likely reflecting their roles in cell proliferation or repair." (PMID 29339782, 2018).
liver cirrhosis (1 paper, 2019). "Previously, an elevation of KRT23 levels in the plasma of liver cirrhosis patient was observed when compared with healthy liver subjects." (PMID 31216713, 2019).
Obesity (1 paper, 2026). Accumulation of substantial excess body fat. "Emerging evidence highlights a pivotal role for Krt23+ fibroblasts in obesity‐associated adipose tissue inflammation." (PMID 41524084, 2026).
ovarian tumor (1 paper, 2024). "Similarly, KRT23 overexpression facilitates the migration of ovarian tumor cells through EMT-regulating TGF-β/Smad signaling." (PMID 39771533, 2024).